AFP (alpha fetoprotein)
Diseases named in the same sentence as AFP in open-access papers (continued):
Sharing a sentence is not in itself a finding about the gene and the disease.
teratoma (continued). "The second patient (case No. 4) had malignant recurrence with the yolk sac component (AFP level 994.9 ng/mL) at 5 months of age from a neonatal sacrococcygeal grade II immature teratoma." (PMID 33530223, 2021). "During the diagnosis and follow-up of mediastinal teratoma, it is necessary to monitor serum tumor markers, and lack alpha-feto-protein (AFP) and beta-human chorionic gonadotropin(β-HCG) should be monitored." (PMID 32066478, 2020). "Given the elevated AFP levels, it was considered that his tumor must have contained teratoma or embryonal tumor components, and it was decided to treat the patient with intensive chemotherapy and radiation." (PMID 32868820, 2020). "Elevated serum AFP or β-HCG level indicates a malignant component to the teratoma, such as embryonal carcinoma, endoderm ml sinus tumor, or choriocarcinoma." (PMID 32066478, 2020). "By (almost) all measures, the teratoma was becoming more mature (pathology, AFP levels, and gross appearance); however, this evidence was seemingly contradicted by the radiographs, which showed “persistent” or “recurrent” Immature Teratoma." (PMID 30581564, 2019). "In the recent Malignant Germ Cell Tumor International Collaborative study regarding ovarian immature teratomas, patients with AFP levels higher than 1000 ng/mL were excluded because this level was considered more likely to indicate malignant elements." (PMID 30165903, 2018). "A large number of cells staining positive for the endodermal marker forkhead box protein A2 (FOXA2) was found in all teratomas, with some also containing gland-like structures consisting of cells that contained AFP." (PMID 26777057, 2016). "The addition of a third biomarker, α-fetoprotein (AFP), improved the detection limit for AFP-positive teratomas to >17 mm3." (PMID 26777057, 2016). "Ultrasonography and tumor markers, such as CA125, CA19-9, and alpha-fetoprotein, are common tools used for the early detection and characterization of ovarian masses, such as mature or immature teratomas." (PMID 24726009, 2014). "Tumor markers, including AFP and CA-125, have contributed to the differential diagnosis between teratomas and schwannomas." (PMID 24273602, 2013). "The patients mainly had mature teratoma-positive primaries, elevated prechemotherapy levels of AFP or HCG or a low LDH level." (PMID 12644820, 2003). "Like germinomas, teratomas are often tumor marker negative; while this holds true for pure mature teratomas (MT), immature teratomas (IT) may secrete AFP." (PMID 39959669, 2025). "Univariate analysis identified presurgery alpha-fetoprotein (P = .01), beta-human chorionic gonadotropin (P = .01), initial teratoma pathology (P = .01), and lymph node metastases (P = .02) as significant predictors for teratoma." (PMID 40854169, 2025). "Importantly, normal AFP and β-human chorionic gonadotropin (β-hCG) levels, as seen in our patient and widely reported in mature teratomas, help differentiate these lesions from malignant germ cell tumors or primary hepatic malignancies." (PMID 41573424, 2025). "Univariate analysis showed that prechemotherapy AFP levels (odds ratio [OR], 1.0, P = .01), β-hCG levels (OR, 0.99, P = .01), presence of teratoma in the primary (OR, 2.75, P = .01), and metastatic lesion being lymph node (OR, 3.13, P = .02) were statistically significant." (PMID 40854169, 2025). "In our case, normal AFP and characteristic histopathology confirmed bilateral mature teratomas." (PMID 41255769, 2025). "Biological exploration of mediastinal teratoma requires monitoring of serum tumor markers, a high serum AFP or β-HCG level could indicate a malignant component of the teratoma, such as an embryonic carcinoma, or a choriocarcinoma." (PMID 38281986, 2024). "Importantly, studies have found that about 50% of patients with immature teratomas have abnormal serum AFP levels, with extremely high levels being observed in some cases." (PMID 39421450, 2024).
teratoma (continued). "However, studies have shown a correlation between alpha-fetoprotein (AFP) levels and the recurrence of teratomas." (PMID 39678394, 2024). "HCG elevation was seen in germinoma cases, while AFP elevation was observed in teratomas." (PMID 35205726, 2022). "Necrosis/fibrosis was significantly more likely to be identified in post-chemotherapy residual masses when compared with teratoma or viable GCT when AFP (OR 3.22, 95% CI 2.49-4.15) or bHCG (OR 1.96, 95% CI 1.62-2.36) were normal at the commencement of chemotherapy." (PMID 36059636, 2022). "There is no specific tumour marker for teratomas; however, immature (malignant) teratomas have been associated with elevated AFP (alpha-fetoprotein) levels." (PMID 31220682, 2019). "Only one girl in the immature teratoma group had AFP levels < 1000 ng/mL in our study." (PMID 30165903, 2018). "Three tumors stained for Placental alkaline phosphatase (PLAP, a marker of reproductive system tumors), cytokeratin (CK, a marker for tumor cells of epithelial origin), desmin (DES, a marker of myogenic origin tumor or tissue), and α-fetoprotein (AFP, marker of teratoma)." (PMID 28103575, 2017). "In addition, we observed loose correlations between CEA or AFP levels and teratoma volumes (R2 = 0.23, R2 = 0.29)." (PMID 26777057, 2016). "Serum AFP is an important indicator of the level of the malignancy of the teratoma, and elevated serum β-HCG levels may reflect either the presence of chorionic tissues within the mass or teratoma recurrence." (PMID 26266375, 2015). "As AFP has been used as a marker of endodermal stem cell differentiation, we hypothesize that AFP could have been induced during the endodermal differentiation of an embryonal carcinoma into the three germ layers (teratoma)." (PMID 34518930, 2022). "AFP may increase within the first year of life, and teratomas can also produce AFP." (PMID 36601033, 2022). "In cases of immature teratomas, the levels of AFP may be elevated." (PMID 35937851, 2022). "Moreover, elevated AFP and hCG can sometimes occur with immature teratomas." (PMID 34829327, 2021). "Serum alpha-fetoprotein (AFP) was also ordered, as this tumor marker is often elevated in immature teratomas; the patient's AFP level was elevated to 18.2." (PMID 39445228, 2024). "After chemotherapy and prior to surgery, 36.4% and 27.3% of patients had persistent elevation of traditional serum tumour markers in the teratoma (two LDH, one HCG, one AFP/LDH) and NFVT group (one LDH, one AFP, one HCG), respectively." (PMID 36569509, 2023). "Regarding tumor markers, AFP and CA125 levels were significantly higher in immature teratomas than in mature teratomas." (PMID 37635241, 2023). "This study demonstrates that tumor markers are elevated in germinomas and teratomas, especially HCG in germinomas and AFP in immature teratomas, emphasizing the clinical significance of tissue diagnosis." (PMID 35205726, 2022). "The pathological diagnosis was a mature teratoma; however, mixed GCT including immature teratoma and yolk sac tumor was suspected because serum AFP was elevated." (PMID 36443673, 2022). "Our study verifies miR371 as a good serum marker with sensitivity superior to the classical markers AFP and hCGβ for detection and monitoring of TGCC, except for the teratomas." (PMID 34341387, 2021). "Alpha-fetoprotein (AFP) is elevated in embryonal carcinomas and teratomas, whereas choriocarcinomas and germinomas secrete β-hCG." (PMID 34357128, 2021). "Furthermore, west blotting results showed that the expression levels of the markers of ectoderm (class III β-tubulin), mesoderm (cTnT) and endoderm (AFP) were remarkably up-regulated in MDLS-induced teratomas, suggesting that MDLS could enhance the pluripotency of P19 cells." (PMID 34348786, 2021). "Consistent with this, the expression levels of AFP and cTnT, as markers for endoderm and mesoderm respectively, remarkably up-regulated in MDLS-induced teratomas." (PMID 34348786, 2021).
teratoma (continued). "One patient with NGGCT with high AFP and β-HCG developed recurrence 11 years later with an intrasellar mature teratoma." (PMID 32937871, 2020). "Tumor markers AFP, beta HCG and LDH were raised in all except the patient with mature and immature teratoma." (PMID 31897390, 2019). "Tumor markers like alpha-fetoprotein and β HCG help to suspect a malignant component in teratomas preoperatively." (PMID 30660187, 2019). "A combination of three biomarkers (CEA, AFP, and HCG) was able to detect 87% (7/8) of teratomas with volumes >17 mm3." (PMID 26777057, 2016). "A combination of three plasma biomarkers (CEA, AFP, and HCG) was able to detect teratomas with a volume >17 mm3 and with a sensitivity of more than 87%." (PMID 26777057, 2016). "The teratoma also stained with α-SMA, AFP and GFAP (a marker of the ectoderm), respectively, to further demonstrated the differentiation ability." (PMID 27025901, 2016). "Typically, the comprehensive diagnostic criteria for suspected germinomas in our center include age, sex, the origin of tumor identified by MRI, exclusion from the possibility of teratoma and choriocarcinoma by MRI, β-HCG and AFP level." (PMID 26771195, 2016). "The ability of single biomarkers to detect teratomas were as follows: CEA, 75% (6/8); AFP, 50% (4/8); fibroblast growth factor (FGF), 50% (4/8); HCG, 25% (2/8); and CA-125, 25% (2/8)." (PMID 26777057, 2016). "The alpha-fetoprotein (AFP) levels were known for 46 patients, and two patients with immature teratoma and five with EST had elevated AFP levels that were higher than 100 ng/ml." (PMID 21988930, 2011). "Our patient's normal AFP levels and absence of endocrine symptoms were consistent with a non‐functional mature teratoma." (PMID 41476812, 2026). "Though teratoma traditionally does not produce elevations in STMs, mild AFP elevations can be observed in up to 25% of teratomas owing potentially to hepatoid differentiation or mucinous glandular components." (PMID 39685906, 2024). "The limitation of conventional biomarkers, including Alpha-Fetoprotein (AFP), Beta-Human Chorionic Gonadotropin (β-HCG), and Lactate Dehydrogenase (LDH), lies in their restricted sensitivity and specificity, including for the identification of teratoma." (PMID 38396829, 2024). "Although a low level of AFP-elevation can be due to non-neoplastic reasons, four teratoma patients showed very high AFP levels (135, 281, 365 and 2533 μg/l)." (PMID 34518930, 2022). "In particular, ONB can be differentiated from intracranial immature teratoma for the absence of some increased substances including AFP, b-HCG, and PLAP in serum and cerebrospinal fluid." (PMID 36452830, 2022). "Serum and CSF HCG, and serum and CSF AFP are displayed as scatterplots across histology: germinoma (G), MT, ImT, G + MT, G + ImT, and NGGCTs containing malignant components (YST, CC, EC, and malignant transformation of teratoma)." (PMID 35205726, 2022). "Patient depicted as case 1 (non-seminoma (embryonal carcinoma and teratoma), stage II, intermediate IGCCCG risk group) had high levels of AFP and β-HCG at start of chemotherapy, after which they normalized." (PMID 31597402, 2019). "Multiple publications where cases of immature teratoma are analyzed without taking AFP levels into consideration makes it more difficult to form a credible assessment of this indicator." (PMID 30165903, 2018). "But, in this case, bhCG, AFP and other laboratory tests were normal, which did not support the diagnosis of teratoma." (PMID 27906066, 2016). "Human ALB and AFP were detected between the concentrations of approximately 0.6–1.6 and 1.7–2.9 μg/mL, respectively, in the sera of mice bearing teratomas but not in those of normal mice." (PMID 25875613, 2015). "The exact incidence of pediatric GCTs is not precisely known as approximately 50% of GCTs are benign [pure mature teratoma which do not secrete α-fetoprotein (AFP) and β-human chorionic gonadotropin (β-hCG)] and go unreported." (PMID 22312308, 2012).
teratoma (continued). "None of the grafted animal brains harbored a teratoma (absence of alpha-fetoprotein, cytokeratin, myosin) or other type of tumor as assessed by histological analysis on hematoxylin and eosin (H&E) sections." (PMID 21961042, 2011). "Therefore, AFP and CA125 are useful biomarkers for differentiating mature from immature teratomas." (PMID 37635241, 2023). "However, immature teratomas express AFP, so that they can be nonspecific." (PMID 36805679, 2023). "Furthermore, WT and DKO iPSCs injected into opposite flanks of nude mice, generate teratoma that grow at comparable rates, differentiate into the three germ layers, and express similar levels of germ layer specific markers such as TUJ1 for neuroectoderm, MF20 for mesoderm, and AFP for endoderm." (PMID 30532006, 2018). "Intracranial NGGCTs can show elevated serum and CSF markers like alpha-fetoprotein (AFP), human beta-chorionic gonadotropin (ß-HCG) and placental alkaline phosphatase (PLAP), however, they are not typically elevated in mature teratomas." (PMID 38276973, 2024). "measured the serum levels of AFP and β-HCG in seven patients with intracranial mature teratomas and found no elevated titers, consistent with our case." (PMID 39931213, 2024). "It has been demonstrated that AFP has a prolonged half-life in SCT tumors with a tendency for recurrence (with YST admixture) and in immature teratomas (without YST admixture)." (PMID 37686577, 2023). "Histopathology for the seven cases with isolated serum AFP elevation were germinoma, germinoma with EC, germinoma with MT and YST, germinoma with ImT, NGGCT not otherwise specified, teratoma with somatic-type malignancy, and ImT." (PMID 36995447, 2023). "Out of 18 cases with elevated AFP and without a YST component, two cases had a MT component, 12 cases had an ImT component and one case was teratoma with somatic-type malignancy; 83% at least one teratoma component." (PMID 36995447, 2023). "In contrast, cancer-specific factors associated with major complications were aggressive histology in RPLND specimens (nonseminoma and immature teratoma p = 0.004), more than four cycles of chemotherapy (p = 0.002), salvage RPLND (p < 0.001), and a preoperatively elevated AFP (p < 0.001)." (PMID 37490059, 2023). "Diagnosis of TC involves the evaluation of serum tumor markers alpha-fetoprotein, human chorionic gonadotropin and lactate dehydrogenase, but clinically several types of immunohistochemical markers are more useful and more sensitive in GCT, but not in teratoma." (PMID 29262668, 2017). "In infants and adolescents who do not have underlying hepatic disease, a significant elevation of serum AFP or β-hCG indicates significant “secreting” components of YST or choriocarcinoma, respectively, and rules out pure mature teratoma or seminoma; though seminomas may secrete minimal hCG." (PMID 22312308, 2012).
viral hepatitis (98 papers, 2007 to 2025). An acute or chronic inflammation of the liver parenchyma caused by viruses. "cohort, the prevalence of underlying viral hepatitis was above 25% and approximately 10 percent of patients had a preoperative plasma AFP above 20 ng/mL." (PMID 37404757, 2023). "Measuring AFP three or more times within the two years prior to being diagnosed with HCC in viral hepatitis cases was associated with decreased overall survival." (PMID 38201578, 2023). "A low serum irisin level was associated with male, history of viral hepatitis, and a high AFP level (P < 0.05 for all)." (PMID 31976024, 2019). "Several additional significant clinical-pathologic differences in HCC were also observed according to underlying viral hepatitis status, including AFP production." (PMID 22681852, 2012). "Viral hepatitis-associated ICC patients were found had elevated serum alpha-fetoprotein levels as compared with seronegative ICC patients." (PMID 22799744, 2012). "This is illustrated by the article in this special edition by N. Mousa and coworkers describing the association of alpha fetoprotein (AFP) and liver steatosis in genotype 4 infection in chronic viral hepatitis." (PMID 23209913, 2012). "Finally, some risk factors of HCC patients, like AFP levels and viral hepatitis, were missing from the database, which may reduce the predictive power of the nomogram." (PMID 36700197, 2022). "HCC typically manifests in patients with viral hepatitis or cirrhotic backgrounds, accompanied by elevated AFP levels, intense arterial-phase hyperenhancement, and subsequent portal/equilibrium-phase contrast washout." (PMID 40313453, 2025). "Elevated levels of baseline AFP, NLR, AAR, ALBI score, SII, and decreased CALLY index and N/CRP ratio were associated with vascular invasion and final tumor size in viral hepatitis." (PMID 40181742, 2025). "Both groups were predominantly male, with similar proportions of patients with viral hepatitis, as well as the Child-Pugh scores, AFP levels, and tumor counts, indicating similar general health and liver function status between the groups." (PMID 41357217, 2025). "In our study, the diagnostic performance of AFP and PIVKA-II in the CHB cohort was comparable to that observed in the CHC cohort, suggesting that both biomarkers demonstrate similar utility across chronic viral hepatitis etiologies." (PMID 41301746, 2025). "In summary, immunotherapy combined with anti-angiogenetic agents holds promise as a superior therapeutic strategy in patients diagnosed with BCLC C stage, ECOG 1, EHS, AFP levels<400ng/ml, and viral hepatitis positivity, particularly HBV." (PMID 39038010, 2024). "Patients with HCC were older, with lower ALBI, better liver function, lower AFP, and more antiviral therapy for viral hepatitis as time goes from period I to II." (PMID 38452155, 2024). "In such cases, serum liver function tests, serology for viral hepatitis, alpha-fetoprotein (AFP), carcinoembryonic antigen (CEA), carbohydrate antigen 19-9 (CA19-9), and imaging studies with tumor characterization are part of the initial diagnostic workup." (PMID 37174934, 2023). "The two groups were similar in terms of sex, age, ECOG‐PS score, Child–Pugh grade, albumin‐bilirubin (ALBI) score, modified ALBI grade, BCLC stage C, AFP level, viral hepatitis, PVTT type, number of tumors, hepatic vein invasion, and extrahepatic metastasis." (PMID 36951443, 2023). "HCC is dominant in men over 45 years old, who have viral hepatitis and elevated AFP, and these factors can help to confirm its diagnosis." (PMID 36600110, 2023). "For treatment outcomes to immunotherapy, the clinico-pathological characteristics in patients which correlated with preferable PFS were BCLC B disease, viral hepatitis positivity, AFP less than 400 ng/ml, EHS/MVI, and prior local therapy." (PMID 37598406, 2023).